BRD3 (bromodomain containing 3)
Diseases named in the same sentence as BRD3 in open-access papers (continued):
Sharing a sentence is not in itself a finding about the gene and the disease.
nasopharyngeal carcinoma (4 papers, 2010 to 2022). A carcinoma arising from the nasopharyngeal epithelium. "BRD3-dependent functional relationships with the cell cycle control machinery in normal cells are poorly understood, although forced expression of BRD3 down-regulates the RB–E2F pathway in nasopharyngeal carcinoma cells." (PMID 25849938, 2015).
gastric cancer (3 papers, 2020 to 2024). A primary or metastatic malignant neoplasm involving the stomach. "ARV-825 induced degradation of BRD4, BRD2, BRD3, c-MYC, and polo-like kinase 1 (PLK1) proteins in four gastric cancer cell lines." (PMID 34733788, 2021). "BRD4, BRD2, and BRD3 were abundantly expressed in MGC803, HGC27, AGS, SGC7901, BGC823, and SNU-216 cells, implying that the BET proteins were diffusely expressed in gastric cancer cells." (PMID 34733788, 2021).
glioma (3 papers, 2020 to 2025). A benign or malignant brain and spinal cord tumor that arises from glial cells (astrocytes, oligodendrocytes, ependymal cells). "In CGGA, lower expression of BRD2/BRD4 and higher expression of BRD3 in the primary glioma datasets was associated with survival superiority of patients." (PMID 33135348, 2020). "Additionally, BRD4 expression is associated with reduced survival in IDH-mutant gliomas, while BRD3 expression is linked to poorer outcomes in IDH-wildtype gliomas." (PMID 40565099, 2025). "Analysis of clinical TCGA low grade glioma and glioblastoma data shows BRD4 gene expression correlates with decreased survival only in IDHmut glioma, while BRD3 gene expression correlates with reduced patient survival only in IDHwt glioma." (PMID 35467128, 2022). "Overall, these data suggest that increased BRD4 activity results in enhanced malignancy only in IDHmut glioma, particularly astrocytomas, whereas increased BRD3 activity results in enhanced survival only in IDHwt glioma." (PMID 35467128, 2022). "A total of 680 TCGA RNA‐s Equation (TCGA‐seq) samples and 281 CGGA RNA‐s Equation (CGGA‐seq) samples were evaluated to investigate the relation between mRNA expression of BET family members BRD2/BRD3/BRD4, and overall survival (OS) in glioma patients." (PMID 33135348, 2020). "Here, we validated that BRD4, not BRD2 or BRD3, has value in targeted glioma therapy." (PMID 33135348, 2020). "We evaluated BRD4, not BRD2 or BRD3, has value in targeted glioma therapy." (PMID 33135348, 2020). "Therefore, it seems that BRD2/BRD3 has no value in targeted glioma therapy." (PMID 33135348, 2020). "In recurrent glioma, BRD4 expression (P < .05), but not BRD2/BRD3 expression (P > .05), resulted in significant differences in OS." (PMID 33135348, 2020). "BETi JQ1 demonstrated significant inhibition of BET activity but limited clinical success, as seen with the withdrawal of the Phase II trial for birabresib (MK-8628, OTX015), a selective inhibitor of BRD2/BRD3/BRD4, due to lack of efficacy in IDH-wildtype gliomas." (PMID 40565099, 2025).
neuroblastoma (3 papers, 2016 to 2022). Neuroblastoma (NB) is the most common solid, extracranial childhood tumor. "It precisely targets BRD4 proteins, induces the degradation of BRD2 and BRD3, and has a strong antitumor effect on neuroblastoma." (PMID 36438198, 2022). "Mechanistically, the quinone-containing compound nanaomycin induced neuroblastoma cell death but also activated the Nrf2-antioxidant signaling pathway, and the BET bromodomain proteins BRD3 and BRD4 formed a protein complex with Nrf2." (PMID 27764794, 2016). "All the cell lines tested expressed BRD2, BRD3 and BRD4 at least two times more than normal mesenchymal stem cells (MSCs), except the SK-N-MC cells, potentially because of their neuroblastoma origin." (PMID 27006472, 2016).
squamous cell carcinoma (3 papers, 2012 to 2022). A carcinoma arising from squamous epithelial cells. "The recent development of potent and highly specific Kac competitive inhibitors for BET BRDs provides a compelling case for targeting these BRDs for the treatment of an extremely aggressive subtype of squamous cell carcinoma that is caused by chromosomal rearrangement of BRD3 or BRD4 with NUT." (PMID 22464331, 2012). "Significant associations between BRD3 rs2427964 and worse OS were found in adenocarcinoma (aHR = 2.78, 95% CIs = 1.77–4.35, P = 8× 10−6) but not in squamous cell carcinoma (aHR= 1.35, 95% CIs = 0.81–2.25, P = 0.25; P < 0.05 for the homogeneity test)." (PMID 34605158, 2022).
chondrosarcoma (2 papers, 2023). A malignant cartilaginous matrix-producing mesenchymal neoplasm arising from the bone and soft tissue. "Furthermore, BRD3, together with BRD4, was shown to regulate the expression of matrix metalloproteinases (MMP) under pro-inflammatory conditions in chondrosarcoma cells." (PMID 38137409, 2023).
colorectal cancer (2 papers, 2024 to 2025). A primary or metastatic malignant neoplasm that affects the colon or rectum. "Targeting BRD3 also effectively suppresses nuclear TYRO3-driven metastasis in colorectal cancer, underscoring BRD3 as a promising therapeutic target to prevent tumor dissemination." (PMID 41583469, 2025). "In a colorectal cancer model, PROTAC-mediated degradation of BET proteins (BRD2, BRD3, and BRD4) in tumor cells induces immunogenic cell death and activates DR5-mediated apoptosis." (PMID 41583469, 2025). "In colorectal cancer, nuclear TYRO3 phosphorylated the epigenetic regulator BRD3 to regulate genes involved in colorectal cancer metastasis." (PMID 39062902, 2024).
Ewing sarcoma (2 papers, 2016). A small round cell tumor that lacks morphologic, immunohistochemical, and electron microscopic evidence of neuroectodermal differentiation. "To directly assess the relevance of targeting BET bromodomain proteins signaling in Ewing Sarcoma disease, we first evaluated the messenger RNA expression level of BRD2, BRD3 and BRD4 in ten human Ewing Sarcoma cell lines." (PMID 27006472, 2016). "This reversal of EWS/FLI gene expression pattern was exclusively mirrored through siRNA-mediated knockdown of BRD3 and BRD4 but not BRD2, suggesting that BRD3 and BRD4 may be critical epigenetic regulators in Ewing sarcoma." (PMID 27635231, 2016).
glioblastoma (2 papers, 2019 to 2022). The most malignant astrocytic tumor (WHO grade IV). "Even though BRD3 inhibitors have not been studied as much as those of the BRD2/4, it has been observed that I-BET151, a pan-BET inhibitor that targets BRD3, halts the progression of the cell cycle and decreases cell proliferation in vitro and in vivo by targeting lncRNA HOTAIR in glioblastoma." (PMID 31850055, 2019).
liver cancer (2 papers, 2017 to 2024). An epithelial or non-epithelial malignant neoplasm that arises from the liver. "We find that both BRD2 and BRD4 but not BRD3 are required for liver cancer cell growth, and even transient BET suppression using pan-BETis (JQ-1 and ABBV075) is sufficient to impede cell proliferation and xenograft tumor growth." (PMID 39872506, 2024).
ovarian carcinoma (2 papers, 2020 to 2022). A malignant neoplasm originating from the surface ovarian epithelium. "Our results showed that the protein level of BRD2, BRD3, BRD4, and BRDT in ovarian cancer cell lines was all subsided associated to the normal breast cell (P < 0.05)." (PMID 35371325, 2022). "In addition, overexpression of BRD3 and BRDT mRNA was associated to a better-quality OS for patients with ovarian carcinoma receiving Taxol and concurrent Taxol+Platin-based chemotherapy." (PMID 35371325, 2022). "Concerning clinical stages, BRD2 and BRD3 in advanced stage (III+IV), and BRDT in all clinical stages (I+II, III+IV) were associated with the better OS in ovarian cancer patients, although high BRD4 mRNA level showed worse OS in early-stage (I+II) patients with ovarian cancer." (PMID 35371325, 2022). "We observed that high levels of BRD2, BRD3, and BRDT indicated a better prognosis, whereas BRD4 predicted poor clinical outcomes in patients with ovarian carcinoma." (PMID 35371325, 2022). "As for BRD3, we found that BRD3 expression was related to better OS in endometrioid ovarian carcinoma and stage III+IV ovarian carcinoma patients, as well as all patients managed with Taxol and concurrent Taxol+Platin based chemotherapy." (PMID 35371325, 2022). "The BRD2, BRD3, and BRDT mRNA expression in the human ovarian cancer cell lines were all considerably downregulated in relationship with those in a normal ovarian cell line (P < 0.05)." (PMID 35371325, 2022). "A recent study reported that BET proteins regulated RAD51 in ovarian cancer cells, and we showed that knockdown of each BET family member (BRD2, BRD3, and BRD4) in DMS273 cells led to downregulation of Rad51 expression." (PMID 33134168, 2020).
pulmonary fibrosis (2 papers, 2019 to 2022). Chronic progressive interstitial lung disorder characterized by the replacement of the lung tissue by connective tissue, leading to progressive dyspnea, respiratory failure, or right heart failure. "Importantly, our finding that Brd3 and Brd4, but not Brd2, are involved in NOX4 regulation by TGF-β suggests that a degree of selectivity may be possible when considering BET inhibitors as possible therapeutic agents in pulmonary fibrosis." (PMID 31119153, 2019).
Thrombocytopenia (2 papers, 2022 to 2023). A reduction in the number of circulating thrombocytes. "Thrombocytopenia is linked to inhibition of BRD3, functionally required during megakaryocyte and erythroid cell maturation." (PMID 35444289, 2022). "Similarly, thrombocytopenia may result from the inhibition of BRD3 during erythroid cell maturation, a process in which BRD3 has been shown to be involved." (PMID 36982740, 2023). "Current BET inhibitors do not discriminate between the paralogs BRD4, BRD2 and BRD3, resulting in a narrow safety window, with thrombocytopenia as the main dose-limiting toxicity." (PMID 35444289, 2022).
triple-negative breast carcinoma (2 papers, 2020 to 2021). An invasive breast carcinoma which is negative for expression of estrogen receptor (ER), progesterone receptor (PR), and human epidermal growth factor receptor 2 (HER2). "The BRD4 degrader MZ1 potently and rapidly induces preferential removal of BRD4 over BRD2 and BRD3, and has shown high efficacy in ovarian and triple-negative breast cancer in vivo." (PMID 33958721, 2021). "It is also known that BRD2 promotes EMT, while BRD3 and BRD4 negatively regulate this process in triple-negative breast cancer." (PMID 32961679, 2020).
acute myeloid leukemia (1 paper, 2025). Acute myeloid leukemia (AML) is a group of neoplasms arising from precursor cells committed to the myeloid cell-line differentiation. "It induces CRBN-dependent degradation of BET family proteins, including BRD2, BRD3, and BRD4, in human acute myeloid leukemia (AML) cells with a DC50 of 100 nM." (PMID 40507351, 2025).
Alzheimer disease (1 paper, 2017). A progressive, neurodegenerative disease characterized by loss of function and death of nerve cells in several areas of the brain leading to loss of cognitive function such as memory and language. "Here we tested the effect of JQ1—a small-molecule inhibitor of the chromatin readers BRD2, BRD3, BRD4 and BRDT—on brain function and show that JQ1 is able to enhance cognitive performance and long-term potentiation in wild-type animals and in a mouse model for Alzheimer’s disease." (PMID 28949335, 2017).
autoimmune uveitis (1 paper, 2026). An autoimmune form of uveitis (disease). "This study validates BRD3 protein degradation as a promising clinical strategy against eye inflammation and demonstrates the feasibility of treating autoimmune uveitis with PROTACs." (PMID 41585484, 2026). "Overall, we identified D072 as a specific degrader of BRD3 in the murine system that can inhibit proinflammatory microglia in autoimmune uveitis, potentially providing a therapeutic approach for uveitis." (PMID 41585484, 2026).
breast tumor (1 paper, 2022). "Despite this, BRD2, BRD3, and BRDT expression were discovered to be low in normal breast tissues, while it was shown to be high and medium in the cytoplasmic and membranous parts of breast tumor tissues, respectively." (PMID 35371325, 2022).
colorectal tumors (1 paper, 2017). "Our data revealed high-frequency mutations in BRD4 or BRD3 or both in 79 % (23/29) of colorectal tumors, which is, therefore, a novel finding." (PMID 29296220, 2017).
developmental delay (1 paper, 2024). "Moreover, other risk genes for developmental delay, such as BRD3, KBTBD7, and GATA3, also peaked during this stage, whereas SOX2 displayed high expression in a later lineage." (PMID 39363111, 2024).
endometrioid ovarian carcinoma (1 paper, 2022). "However, high mRNA expression of BRD3 for endometrioid ovarian cancer was associated with favorable OS, HR= 0.06 (0.01 - 0.51), P= 0.00044." (PMID 35371325, 2022).
hyperuricemia (1 paper, 2021). An abnormally high level of uric acid. "In response to hyperuricemia, renal expression of Brd2 was induced, Brd4 upregulated, but Brd3 expression was not altered; administration of I-BET151 abolished expression of Brd2 and Brd4, but did not affect Brd3 expression in the kidney of HN." (PMID 33664670, 2021).
liver fibrosis (1 paper, 2025). "Furthermore, Western blot analysis of liver tissues revealed elevated expression of BRD4, but not BRD2 and BRD3 in the CDAA-HFD group, again suggesting BRD4 as the major protein that mediates liver fibrosis." (PMID 40756370, 2025).
lymphoma (1 paper, 2024). A malignant (clonal) proliferation of B- lymphocytes or T- lymphocytes which involves the lymph nodes, bone marrow and/or extranodal sites. "This is consistent with previous findings that IBET preferentially targets BRD4 over BRD2 and BRD3, and that lymphoma Raji cells stably expressing a dominant negative BRD4 displayed near identical global effects on gene expression to those treated with the BET inhibitor JQ1." (PMID 38884356, 2024).
medulloblastoma (1 paper, 2013). A malignant, invasive embryonal neoplasm arising from the cerebellum. "We re-analyzed these data, and detected significantly higher BRD3 expression levels in medulloblastomas compared to normal human cerebellum (P <0.01)." (PMID 24231268, 2013). "Taken together, BRD2, BRD3 and BRD4 are expressed in primary medulloblastomas." (PMID 24231268, 2013).
multiple myeloma (1 paper, 2023). "The proteome analyses of the same SCDCLs identified two pivotal proteins in the extracted protein signature, i.e., (i) BRD3 which is a family member of the BET proteins and (ii) the TNF receptor TNFRSF6B whose gene possess a super-enhancer in multiple myeloma cells." (PMID 37719017, 2023).
myelofibrosis (1 paper, 2024). A partial or complete replacement of the bone marrow stroma by fibrous tissue. "This compound is an experimental myelofibrosis and cancer drug (clinicaltrials.gov, NCT04454658, accessed July 21, 2023) that acts as an inhibitor of BET bromodomain proteins, specifically BD2 domain of BRD2, BRD3 and BRD4." (PMID 38526670, 2024).
oral carcinoma (1 paper, 2025). "A preclinical study of oral carcinoma cell lines, Ca9-22, HSC-2, HSC-3, HSC-4, demonstrated that Kaempferol and withanolide D kaempferol and withanolide D effectively inhibited oncogenic proteins, CDK2, and BRD3, inducing cytotoxicity via autophagy and caspase activation." (PMID 41346617, 2025).
osteoporosis (1 paper, 2016). A condition of reduced bone mass, with decreased cortical thickness and a decrease in the number and size of the trabeculae of cancellous bone (but normal chemical composition), resulting in increased fracture incidence. "Recently, we showed that NMP acts as a low affinity bromodomain inhibitor for BRD2, BRD3, BRD4, and BRDT and has potential for osteoporosis treatment." (PMID 27110299, 2016).
pancreatic ductal adenocarcinoma (1 paper, 2017). An infiltrating adenocarcinoma that arises from the epithelial cells of the pancreas. "To validate the screening results, we knocked down the genes encoding BRD2, BRD3, or BRD4 in human pancreatic ductal adenocarcinoma KP-4 cells and determined their effects on autophagy by monitoring the levels of the lipidated form of LC3 (LC3II)—a marker of autophagosome formation/accumulation." (PMID 28525743, 2017).
pancreatic NETs (1 paper, 2020). "In our study, we demonstrate that AtT20 cells express the BET family members Brd2, Brd3 and Brd4, with Brd2 being the most abundant, which is similar to data reported for MEN1-associated mouse pancreatic NETs and human pancreatic and bronchial NET cell lines." (PMID 31935194, 2020).
soft tissue tumors (1 paper, 2024). "Beyond the epithelial tissue, a few cases of soft tissue tumors have been reported to carry BRD3/4::NUTM1 fusion genes, suggesting that the fusion gene can also collaborate with mesoderm-derived mesenchymal gene regulatory networks (GRNs) to drive NC." (PMID 38724194, 2024).
uveitis (1 paper, 2026). An inflammatory process affecting a part of or the entire uvea. "Nevertheless, the potential role of D072 in mammalian models has yet to be explored, and the precise mechanisms by which BRD3 influences uveitis pathogenesis remain incompletely understood." (PMID 41585484, 2026). "This study identified a BRD3 degrader that reduces the inflammatory level of microglia cells in uveitis by decreasing H3K18ac." (PMID 41585484, 2026). "In conclusion, a specific BRD3 degrader PROTAC D072 was identified, which showed protective effects for uveitis by inhibiting the BRD3/H3K18ac/CCL5 axis in proinflammatory retinal microglia." (PMID 41585484, 2026). "In this study, we reported that D072 has a certain anti-inflammatory effect on uveitis and LPS-stimulated microglia by degrading BRD3." (PMID 41585484, 2026). "Further studies are needed to better elucidate BRD3’s role and to explore the applicability of D072 as a clinical therapeutic strategy for uveitis." (PMID 41585484, 2026). "Therefore, D072’s therapeutic effects in uveitis may be mediated through the BRD3-H3K18ac axis and its impact on inflammatory microglia." (PMID 41585484, 2026).